MR1 (major histocompatibility complex, class I-related)
Diseases named in the same sentence as MR1 in open-access papers (continued):
Sharing a sentence is not in itself a finding about the gene and the disease.
breast carcinoma (7 papers, 2018 to 2025). "Further in vitro experiments demonstrate that when MAIT cells are activated by E. coli in an MR1-dependent manner and co-cultured with breast cancer cell lines, they predominantly produce IL-17A while exhibiting a diminished Th1 or cytotoxic response." (PMID 40746558, 2025). "Although the addition of Ac-6-FP increased the expression of MR1 in breast cancer cells, the addition of Ac-6-FP to the breast cancer cells did not affect the response of TCR10-59." (PMID 39451228, 2024). "In this study, we analyzed MR1-restricted TCRs obtained from tumor-infiltrating lymphocytes (TILs) from breast cancer patients." (PMID 39451228, 2024). "In this study, we analyzed MR1-restricted TCRs obtained from the TILs of two breast cancer patients." (PMID 39451228, 2024). "We have reanalyzed the MR1-restricted TCRs that reacted to breast cancer cells and shown that they responded to some breast cancer cell lines but not to other cancer cell lines." (PMID 39451228, 2024). "MR1 expression was also observed on the cell surface of the other breast cancer cell lines and colon, lung, myeloid, and lymphoid cancer cell lines when these cells were treated with Ac-6-Fp." (PMID 39451228, 2024). "One possible explanation of our results is that MR1 can present an antigen produced in some breast cancer cells and MR1-restricted TCR-expressing T cells infiltrate into tumors in antigen-dependent manner." (PMID 39451228, 2024). "In contrast, breast cancer (P < .001), renal cancer (P < .0048), glioma (P < .0234), and thyroid cancer (P < .0395) have significantly higher expression of MR1 compared to their respective normal tissue." (PMID 33948562, 2021). "We found that MAIT cells are readily activated by breast carcinoma cells and that this activation is dependent on prior bacterial exposure of the carcinoma cells and can be blocked by an anti-MR1 antibody." (PMID 30208917, 2018). "Breast carcinoma cells that had been exposed to Escherichia coli activated MAIT cells in an MR1-dependent manner." (PMID 30208917, 2018). "We therefore used intracellular flow cytometric staining to confirm that the human breast carcinoma cell line MDA-MB-231 endogenously expresses the MR1 antigen-presenting molecule." (PMID 30208917, 2018). "We next investigated the ability of human breast carcinoma cells to activate MAIT cells in an MR1-dependent manner." (PMID 30208917, 2018). "Together, these results demonstrate that MAIT cells are activated in a TCR-, MR1-, and microbe-dependent manner by MDA-MB-231 breast carcinoma cells." (PMID 30208917, 2018). "Kishi and colleagues described expansions of HLA-agnostic T cells in the TILs of 2 patients with breast cancer in Japan who responded to MCF-7 breast cancer cells (MR1*01/*02) but not MR1-KO MCF-7 cells." (PMID 39744940, 2025). "MR1-restricted, cancer-reactive T cells bearing this TRAJ42-containing motif have been observed expanded and PD1+ among tumor-infiltrating lymphocytes in breast cancer." (PMID 40763744, 2025). "Our findings suggest the existence of a novel class of MR1-restricted TCRs whose antigen is expressed in some breast cancer cells and binds to MR1 depending on the K43 residue of MR1 but without being influenced by Ac-6-FP." (PMID 39451228, 2024). "Our MR1-restricted TCR reacted to some breast cancer cells but not to normal breast cells or other cancer cells." (PMID 39451228, 2024). "They did not react to another breast cancer cell line, ZR-75-1, although it showed a higher surface expression of MR1." (PMID 39451228, 2024). "Furthermore, the expansion of these breast cancer–reactive, MR1-restricted T cells within breast cancer TIL without described pathology indicates that these cells are safe in vivo." (PMID 39744940, 2025). "Furthermore, the reactivity of our TCR to breast cancer cells was not inhibited by Ac-6-FP- or MR1-specific antibodies." (PMID 39451228, 2024).
breast carcinoma (continued). "Thus, MR1-restricted TCRs derived from the TILs of breast cancer patients reacted to an antigen expressed in MCF7 or MDA-MB-231 breast cancer cells but not expressed in other cancer cell lines, including the ZR-75-1 breast cancer cell line." (PMID 39451228, 2024). "Our MR1-restricted TCRs reacted to MCF7 cells and MDA-MB-231 breast cancer cells but did not react to other cancer cell lines." (PMID 39451228, 2024). "Additionally, research has shown that MR1-restricted TRAV1-2+ and TRAV26-1+ TCRs identified from the tumor-infiltrating T cells of breast cancer patients specifically respond to some breast cancer cell lines but not to other cancer types." (PMID 40746558, 2025). "MDA-MB-231 breast carcinoma cells were exposed to killed E. coli bacteria or mock-treated, then washed and coincubated with the isolated CD161+ cells in the presence or absence of an anti-MR1 blocking antibody." (PMID 30208917, 2018). "Furthermore, the reactivity of our MR1-restricted TCRs to breast cancer cells was not inhibited by MR1 antagonist, Ac-6-FP, or anti-MR1 mAb, while that of MAIT cells and the reported MR1-restricted T cells was inhibited by 6-FP, Ac-6-FP, and anti-MR1 mAb." (PMID 39451228, 2024).
glioma (7 papers, 2012 to 2026). A benign or malignant brain and spinal cord tumor that arises from glial cells (astrocytes, oligodendrocytes, ependymal cells). "In summary, our findings suggest that MR1 is a prognostic marker for glioma patients and high expression is associated with poor OS." (PMID 33948562, 2021). "Because grade IV glioma (GBM) is the most common adult glioma and is an incurable disease, associated with 100% recurrence, we analyzed MR1 mRNA expression levels in primary and recurrent GBM tumors from the TCGA via GlioVis." (PMID 33948562, 2021). "IDH mutation and MR1 expression are independent factors affecting the clinical outcome of glioma patients." (PMID 33948562, 2021). "An affinity-matured variant of MR1, termed MR1-1, with increased affinity to EGFRvIII, was generated for targeted glioma therapy." (PMID 22400035, 2012). "Thus, we conclude that MR1 is an independent prognostic factor, where overexpression is associated with poor OS for patients with all grades of glioma." (PMID 33948562, 2021). "Thus, there might a mechanistic connection between IDH mutation and MR1 expression in primarily lower grade IDH-mutant gliomas." (PMID 33948562, 2021). "In glioblastoma (GBM), one of the most aggressive glioma malignancies, higher MR1 expression has been correlated with poor prognosis." (PMID 40746558, 2025). "Alongside MS and glioma, our findings in AD show a relatively comparable effect, as elevated MR1 levels are correlated with increased Aβ only in the most vulnerable area—the CA1 region of the hippocampus." (PMID 36944969, 2023). "We have recently reported that the overexpression of MR1 correlates with a worse prognosis in patients with glioma." (PMID 36944969, 2023). "Currently, little is known about the MR1/MAIT cell axis in neurological diseases with limited investigation into only five neurological diseases including glioma, MS, ischemia, experimental autoimmune encephalomyelitis, and cerebral palsy." (PMID 36944969, 2023). "To understand the transcriptomic landscape of MR1 low versus high gliomas, we looked at global gene expression levels in these 2 groups based on glioma grade." (PMID 33948562, 2021). "To understand the effect of MR1 overexpression in glioma, we analyzed the transcriptomic profile of MR1 high- versus MR1 low-expressing gliomas." (PMID 33948562, 2021). "This correlation of MR1 expression by the GBM cells and immune infiltration will need to be further investigated in a mouse model experimental setting to validate correlation and understand the role of MR1 axis in the glioma microenvironment." (PMID 33948562, 2021). "Epigenetic modification of genes is a hallmark feature of many cancers; thus, we assessed the methylation status of MR1 promoter specific CpG sites in all grades of MR1 high and low gliomas." (PMID 33948562, 2021). "To understand the effect of glioma MR1 expression on patient clinical outcome, we analyzed MR1 expression with the patient’s OS data in all grades of glioma." (PMID 33948562, 2021). "Our in silico analysis shows that MR1 expression is a predictor of clinical outcome in glioma patients and is potentially regulated at the epigenetic level, resulting in immune-related genes dysregulation." (PMID 33948562, 2021). "In glioma specifically, we validated MR1 expression by histology, elucidate transcriptomic profiles of MR1 high versus low gliomas." (PMID 33948562, 2021). "To understand the mechanism of MR1 expression in glioma, we studied the DNA methylation pattern of promotor regions of the MR1 gene." (PMID 33948562, 2021). "Using histology, we validated MR1 expression at the protein level in grade IV primary versus recurrent glioma and correlated MR1 expression with immune cell infiltration." (PMID 33948562, 2021). "Using in silico analysis, we identified transcription factors (TFs) with potential MR1 binding sites and found that they are differentially expressed in MR1 high- versus low-expressing gliomas." (PMID 33948562, 2021).
glioma (continued). "This implies that although MR1 is differentially expressed in many solid cancers, the correlation between MR1 expression and OS is glioma-specific." (PMID 33948562, 2021). "MR1 is overexpressed in many solid cancers, and this overexpression is correlated with poor overall survival in glioma patients from TCGA." (PMID 33919687, 2021). "Median survival in days for glioma stratified by MR1 expression showed a statistically significant difference in OS between MR1 high- versus low-expressing tumors (grade II: P < .00032, grade III: P < .0001, and grade IV: P < .0021)." (PMID 33948562, 2021). "We found that 4 of 26 predicted TFs (IRF1, IRF2, CEBPB, and PRDM1) were upregulated at the mRNA level in MR1 high gliomas." (PMID 33948562, 2021). "In the present work, we investigated the expression patterns of MR1 in all grades of glioma and its impact on patient OS." (PMID 33948562, 2021). "Taken together, these results showed an upregulation of TFs that can bind to the MR1 promoter region resulting in upregulation of MR1 in gliomas." (PMID 33948562, 2021). "We then compared MR1 expression levels and patient OS in several common solid cancers including glioma." (PMID 33948562, 2021). "Notably, MAIT cell-deficient Mr1-/- mice displayed reduced survival after GL261 tumor induction, suggesting a protective role for MAIT cells in higher grade gliomas." (PMID 41610383, 2026). "MAIT cells have also demonstrated the ability to effectively lyse GBM cells in an MR1-dependent manner at higher effector-to-target ratios, underscoring their potential to target gliomas via MR1-antigen recognition and highlighting new avenues for glioma immunotherapy." (PMID 40746558, 2025). "However, only in glioma does disease severity and overall survival correlate with higher MR1 gene and protein expression." (PMID 36944969, 2023). "In glioma and MS, increased MR1 expression correlates with a worsening prognosis of the disease." (PMID 36944969, 2023). "We found that MR1 is primarily expressed by the glioma cells." (PMID 33948562, 2021). "In addition, to precisely target this pathway for therapeutic benefit, the significance and level of overexpression of MR1 on glioma cells as well as on possibly other immune cells need to be better characterized using preclinical models." (PMID 33948562, 2021). "MR1 overexpression correlates with immune cell infiltration and drives diverse genetic changes that are specific to each grade and potentially promote an immune-suppressed state in glioma, enabling tumor progression." (PMID 33948562, 2021). "For MR1 high- versus low-expressing gliomas, grade II had 66 versus 180 samples with 23 485 genes differentially expressed; grade III had 64 versus 196 samples with 24 053 genes differentially expressed; and grade IV had 90 versus 61 samples with 22 962 genes differentially expressed." (PMID 33948562, 2021). "TFs with binding sites on MR1 promoter are differentially expressed in MR1 high versus low glioma and may regulate MR1 gene expression." (PMID 33948562, 2021). "MR1 overexpression correlated with decreased MR1 gene methylation and upregulation of predicted MR1 promoter binding TFs, implying MR1 gene methylation might regulate MR1 expression in glioma." (PMID 33948562, 2021). "In the current study, we demonstrate that MR1 expression is a predictor of OS in glioma patients." (PMID 33948562, 2021). "MR1 is overexpressed in all grades of glioma and many other solid cancers." (PMID 33948562, 2021). "However, only in glioma, MR1 overexpression correlated with poor overall survival and demonstrated global dysregulation of many immune-related genes in an MR1-dependent manner." (PMID 33948562, 2021). "Finally, we validated expression levels of TFs that might regulate MR1 expression using qPCR in glioma samples." (PMID 33948562, 2021). "Overall, this effect of MR1 on glioma survival was independent of IDH mutation status." (PMID 33948562, 2021).
glioma (continued). "Analysis of DNA methylation showed hypomethylation of CpG sites for the MR1 promoter in grade II and III glioma, which can explain the upregulation of MR1 gene expression in these groups." (PMID 33948562, 2021). "We observed that MR1 high-expressing grade II and III gliomas shared 3 sites that were hypomethylated between them (cg24441127, cg07025274, and cg23037321)." (PMID 33948562, 2021). "Although expression of MR1 has been demonstrated in a variety of human cancers, there have been no studies analyzing the role of MR1 in glioma." (PMID 33948562, 2021). "However, when analyzing all gliomas together, we saw a statistically significant negative correlation between survival and MR1 expression (P ≤ .0001)." (PMID 33948562, 2021). "We observed that even though MR1 mRNA levels were elevated in several solid cancers (renal, thyroid, and breast) when compared to their non-cancer controls, MR1’s impact on survival was glioma-specific." (PMID 33948562, 2021). "In addition, recent evidence has shown that MR1, a nonclassical MHC class I-like molecule, is epigenetically overexpressed in glioma and correlated with poor overall survival and global dysregulation of many immune-related genes." (PMID 37443750, 2023).
COVID-19 (6 papers, 2020 to 2024). A disease caused by infection with severe acute respiratory syndrome coronavirus 2. "MR1-restricted mucosal-associated invariant T (MAIT) cells in COVID-19: The major histocompatibility complex class I-related molecule (MR1) recognizes vitamin B metabolites from microbes at mucosal sites and plays a putative role in antimicrobial immunity." (PMID 36034704, 2022). "It has been reported that in COVID-19 patients the MAIT cell identification as CD8+CD161+Vα7.2+highly overlaps with the identification done with the MR1/5-OP-RU tetramer, which is considered the most specific method to identify MAITs." (PMID 38211733, 2024). "Projecting data from HD, AM, and AS subjects separately revealed a clear difference between patients and controls with severe reduction in the distinct topography defined by the MR1-5-OP-RU tetramer, suggesting loss of MAIT cells in COVID-19." (PMID 32989174, 2020). "If the hypothesis of MR1-dependent MAIT cells activation in secondary infection of COVID-19 is correct, inhibition mechanisms of this activation could be discussed." (PMID 32849648, 2020). "Along the same line, MAIT cells, which were defined as CD3+ MR1 5-OP-RU tetramer+ or CD3+CD161+Vα7.2+ cells, were significantly reduced in COVID-19 patients compared to healthy controls." (PMID 33546489, 2021). "In a subset of our COVID-19 patient samples (n = 38), we were able to confirm that 80 % (median, range 36–93 %) of the CD3+CD8+CD161+Vα7.2+ cells were also positive for the MR1-tetramer." (PMID 38211733, 2024). "The setting of COVID-19 is, however, quite distinct in that SARS-CoV-2 infection of the lung is unlikely to give rise to MR1-presented antigens." (PMID 32989174, 2020).
leukemia (6 papers, 2020 to 2025). A malignant (clonal) hematologic disorder, involving hematopoietic stem cells and characterized by the presence of primitive or atypical myeloid or lymphoid cells in the bone marrow and the blood. "These cells can be detected using MR1-5-OP-RU tetramers, are restricted to MR1, acquire the hallmark promyelocytic leukemia zinc finger (PLZF) molecule during thymic development, and display an effector-memory phenotype (CD44hi and CD62Llo)." (PMID 32973800, 2020). "MC.7.G5 MR1-restricted T cells can also kill leukemia cells in vivo and prolong the survival of mice." (PMID 33185693, 2020). "Interestingly, the expression of MR1 molecules was found in multiple myeloma (MM) cells and leukemia cell lines such as THP-1 and K562." (PMID 36052080, 2022). "We recently discovered an MR1-restricted T cell clone with an αβ TCR that allowed it to target a wide range of cancer cell lines and also control human leukemia cells in an NSG mouse model." (PMID 39744940, 2025).
autoimmune disease (5 papers, 2015 to 2025). A disorder resulting from loss of function or tissue destruction of an organ or multiple organs, arising from humoral or cellular immune responses of the individual to their own tissue constituents. "The functional regulation of MAIT cells via ligands presented by the nonpolymorphic MR1 has emerged as a cutting‐edge immunotherapeutic strategy for the treatment of infections, autoimmune diseases, tumors, and other conditions." (PMID 41179703, 2025). "The discovery that MR1 presents vitamin B-based small molecule ligands resulted in a rapid expansion of research in this area, which has yielded information on the role of MAIT cells in immune protection, autoimmune disease and recently in homeostasis and cancer." (PMID 32973800, 2020).
Autoimmunity (5 papers, 2015 to 2025). The occurrence of an immune reaction against the organism's own cells or tissues. "Here, the relationship of MR1 splice variants in the context of both infection and autoimmunity remains to be explored." (PMID 32963314, 2020). "Many studies suggest MR1 restricted T cells have an important role in immune contexts, ranging from cancer to autoimmunity and infection." (PMID 36593453, 2023). "With the advent of the MR1 tetramer and the development of comprehensive ex vivo functional assessment, the physiological function of these cells in autoimmunity can be further elucidated." (PMID 26217338, 2015). "Here the authors use an early T cell-specific Bcl11b-deficient mouse that develops autoimmunity through a population of nonconventional MR1-restricted T cells and characterise their function." (PMID 36376329, 2022). "Finally, given the tight regulation of MR1 surface expression and MAIT cell activation, it is possible that microbial activation of MAIT cells could have the unintended consequence of promoting autoimmunity." (PMID 26217338, 2015).